MT-TM (mitochondrially encoded tRNA-Met (AUA/G))
Synonyms: trnM; formerly MTTM
Gene: Mitochondrial transfer RNA gene on chromosome MT (4,402 to 4,469, forward strand). Ensembl gene ENSG00000210112.
Gene-disease validity (ClinGen):
ClinGen rates the evidence that MT-TM causes each of these diseases.
mitochondrial disease (mitochondrial): Definitive.
Diseases named in the same sentence as MT-TM in open-access papers:
MT-TM is named in the same sentence as 1 disease in open-access papers, as found by Europe PMC text mining. Sharing a sentence is not in itself a finding about the gene and the disease.
MT-TM shares sentences with these, for which no sentence is quoted: Mitochondrial myopathy (1 paper).